CFTR (CF transmembrane conductance regulator)
Diseases named in the same sentence as CFTR in open-access papers (continued):
Sharing a sentence is not in itself a finding about the gene and the disease.
cystic fibrosis (continued). "CF is caused by mutation in Cystic Fibrosis Transmembrane Conductance Regulator (CFTR; #602421) gene which encodes a small ATP- and cAMP-dependent chloride channel placed on the apical border of epithelial cells of intestine, respiratory systems, pancreas, gall bladder, and sweat glands." (PMID 29850441, 2018). "A clinical heterogeneity was reported in patients with Cystic Fibrosis with the same CFTR genotype and between siblings with CF." (PMID 30577776, 2018). "Cystic fibrosis, the most common recessive lethal genetic disorder in Caucasians is a result of mutations in the cystic fibrosis transmembrane conductance regulator (CFTR) gene." (PMID 30282922, 2018). "The treatment of cystic fibrosis remains largely symptomatic, although drugs that increase the expression or improve the function of CFTR are being developed." (PMID 30568028, 2018). "Our primary interest is treating the airway disease in cystic fibrosis using a HIV-1 LV vector to introduce a working copy of the cystic fibrosis transmembrane conductance regulator (CFTR) gene into airway epithelial cells." (PMID 31453241, 2018). "CFTR modulators have revolutionized the treatment of individuals with cystic fibrosis by improving the function of existing protein." (PMID 30444886, 2018). "Genetic deletion of the cystic fibrosis transmembrane conductance regulator (CFTR) resulted in cystic fibrosis with features typical of the human disease, including rapidly progressive chronic pancreatitis with eventual pancreatic insufficiency." (PMID 30305676, 2018). "There are currently three approved CFTR modulator treatments available for cystic fibrosis patients, namely Ivacaftor, Orkambi and Symdeko." (PMID 30416447, 2018). "CF is well known to be a chronic inflammatory disease caused by mutations in the gene encoding the cystic fibrosis transmembrane conductance regulator (CFTR), an ATP-gated chloride channel which is expressed, among others, at the apical membrane of epithelial secretory cells of the airways." (PMID 29230506, 2018). "The possibility to culture enteroids at low cost can economically enable high throughput screening to find drugs such as inhibiting EMT for intestinal fibrosis or activating CFTR for cystic fibrosis." (PMID 29464078, 2018). "The role of CFTR in epithelia has been extensively studied in relation to the affected organs in cystic fibrosis." (PMID 27714410, 2017). "In cystic fibrosis patients, thick sputum obturates the airways as a result of CFTR chloride channel defect." (PMID 29228063, 2017). "CFTR, the chloride channel mutated in cystic fibrosis patients, is opened by ATP binding to two cytosolic nucleotide binding domains (NBDs), but pore-domain mutations may also impair gating." (PMID 28944753, 2017). "Cystic fibrosis is an autosomal recessive disorder affecting the cystic fibrosis transmembrane conductance regulator (CFTR)." (PMID 29255267, 2017). "For instance, he suggests that cystic fibrosis is defined, in essence, by an abnormal CFTR ion transport system, but there is an implicit assumption that this abnormal CFTR ion transport system occurs within and influences a broader physiological system." (PMID 27638682, 2017). "Mutations of ABCC6 and CFTR are associated with their decreased functional expression that lead to a rare disease, pseudoxanthoma elasticum and the most frequent severe, monogenic inherited disease, cystic fibrosis, respectively." (PMID 28365738, 2017). "The alteration of CFTR expression can impact BP and both cystic fibrosis patients and mice with reduced CFTR expression have lower BP." (PMID 27815594, 2017). "Evidence provided by a recent longitudinal cohort study involving the North American Cystic Fibrosis Therapeutics Development Network indicates a role of CFTR in gastrointestinal physiology following ivacaftor treatment." (PMID 27475719, 2017).
cystic fibrosis (continued). "For instance, mutations in cystic fibrosis transmembrane conductance regulator (CFTR) gene have been identified in people with cystic fibrosis." (PMID 29263887, 2017). "The cystic fibrosis transmembrane conductance regulator CFTR is a chloride channel, deficiency of which gives rise to cystic fibrosis, the most frequently lethal inherited disease in humans." (PMID 28603639, 2017). "The promising results obtained with PA- or PI5P-loaded ABLs on cells with pharmacologically inhibited CFTR prompted us to evaluate the consequences of ABL treatment on primary monocyte-derived macrophages isolated by 8 patients affected by cystic fibrosis." (PMID 28345623, 2017). "Macrophages (MΦs) with mutations in cystic fibrosis transmembrane conductance regulator (CFTR) have blunted induction of PI3K/AKT signaling in response to TLR4 activation, leading to hyperinflammation, a hallmark of cystic fibrosis disease." (PMID 28883468, 2017). "Cloning of the CFTR gene in conjunction with the discovery of CFTR as a phospho-regulated chloride channel was seminal in the development of high-throughput, target-based initiatives for Cystic Fibrosis drug discovery." (PMID 28409029, 2017). "CF is an autosomal recessive disorder caused by mutations in a gene that encodes for the cystic fibrosis transmembrane conductance regulator (CFTR) protein, an epithelial chloride channel that is widely expressed and is involved in the homeostasis of ions and other metabolites." (PMID 28858208, 2017). "In this respect, microRNAs related to the repression of cystic fibrosis transmembrane conductance regulator (CFTR) gene, which is defective in cystic fibrosis, are of great importance in the development of new type of treatments." (PMID 29286300, 2017). "A similar study on Chilean cystic fibrosis patients concluded that sequencing of coding region and adjacent intronic segments of CFTR gene (OMIM: 602421) has a 90% detection rate, yet there are a lot of variants that have not been identified." (PMID 29178639, 2017). "CF is caused by a mutation in the Cl− channel Cystic fibrosis transmembrane conductance regulator (CFTR), but whether CFTR is present in human alpha cells and regulate glucagon secretion has not been investigated in detail." (PMID 28273890, 2017). "Cystic fibrosis is a common autosomal recessive disease, which is caused by mutations in the gene encoding an anion channel, CF transmembrane conductance regulator (CFTR)." (PMID 28615349, 2017). "In Europe, 1:20 to 1:80 people carry a mutation in the Cystic Fibrosis Transmembrane Conductance Regulator (CFTR) gene, rendering Cystic Fibrosis the most common life-shortening autosomal recessive disorder among Caucasians." (PMID 28499359, 2017). "Ivacaftor is a potentiator of the CFTR chloride channel and is in worldwide clinical use for the chronic treatment of cystic fibrosis in patients." (PMID 29235532, 2017). "Cystic fibrosis is an autosomal recessive genetic disorder caused by mutations in the CFTR gene." (PMID 28983075, 2017). "To further understand the role of defective CFTR on bone growth and metabolism, we utilized the cystic fibrosis rat model." (PMID 29190650, 2017). "Its physiological importance is also reflected in the consequence of CFTR malfunction and cystic fibrosis phenotype which includes pancreas insufficiency, airway mucus obstruction, meconium ileus and high sweat chloride concentrations." (PMID 28615646, 2017). "A total of 11 relations between the CFTR gene and a miRNA were found, which was to be expected since CFTR is the gene responsible for cystic fibrosis and the abstracts chosen dealt in most part with miRNA involvement in this disease." (PMID 28263989, 2017). "Cystic Fibrosis is a severe genetic disease due to defects of the CF Transmembrane Conductance Regulator (CFTR) gene, affecting several organs." (PMID 28553226, 2017).
cystic fibrosis (continued). "Impaired dF508 CFTR folding leads to its premature intracellular degradation and consequently reduces CFTR activity at the plasma membrane of bronchial epithelial cells, characterizing cystic fibrosis as a protein folding disease." (PMID 29255142, 2017). "Epigenetic regulation of expression of cystic fibrosis transmembrane conductance regulator (CFTR) gene by miRNAs has been recently explored by different groups in cystic fibrosis primary bronchial epithelial cells in vitro or from bronchial brushings ex vivo." (PMID 29286300, 2017). "Taken together, we show that this medium throughput assay of CFTR activity has the potential to stratify cystic fibrosis patient-specific responses to approved drugs and investigational compounds in vitro in primary and iPS cell-derived airway cultures." (PMID 28649446, 2017). "CAVD is considered a primary genital form of cystic fibrosis and up to 80% of patients with CAVD have mutations associated with Cystic Fibrosis Transmembrane Conductance (CFTR) gene." (PMID 27597925, 2016). "Although Cif has classical EH activity, it also inhibits CFTR endocytic recycling, leading to a decrease in apical CFTR levels, exacerbating cystic fibrosis symptoms." (PMID 27795395, 2016). "We thank J. Riordan and Cystic Fibrosis Foundation Therapeutics Inc (CFFT) for providing CFTR antibodies." (PMID 27092946, 2016). "Cystic fibrosis is the most common autosomal recessive disorder in white people, and results from mutations in the cystic fibrosis transmembrane-conductance regulator (CFTR) gene, located on the long arm of chromosome 7 in humans." (PMID 27033560, 2016). "CF is caused by mutations in the cystic fibrosis transmembrane conductance regulator [CFTR] gene." (PMID 27919253, 2016). "Furthermore, in Cystic Fibrosis, mutation of one apical channel, the CF transmembrane conductance regulator (CFTR), disturbs a regulatory (proteostasis) network that, inter alia, controls TER." (PMID 26926476, 2016). "A case–control study suggested that the ΔF508 deletion in the CFTR gene in patients with cystic fibrosis, which shows radiological features of BE, is an important protective variant for lung cancer risk." (PMID 27846869, 2016). "Cystic fibrosis, the most common lethal monogenic disease in Caucasians, is caused by mutations in the gene coding for cystic fibrosis transmembrane conductance regulator (CFTR), a 1480-amino acid protein functioning as a chloride channel at the apical membrane from the epithelial cells." (PMID 26976279, 2016). "When the number of functional CFTR channels is further reduced, patients suffer from Cystic Fibrosis." (PMID 27751231, 2016). "The accurate knowledge of CFTR (cystic fibrosis Transmembrane conductance regulator) mutations is of obvious interest in clinical testing, as it improves CF prevention programs of neonatal screening, heterozygote screening in partners of CF patients or partners of carriers." (PMID 27347467, 2016). "In cystic fibrosis, for example, the cystic fibrosis trans-membrane conductance regulator (CFTR/ABCC7) was found to be mutated in many cases." (PMID 28119610, 2016). "Moreover, CF children with severe mutations in cystic fibrosis transmembrane conductance regulator (CFTR) had even lower neutrophil glutamine content compared to children with mild mutations." (PMID 26861387, 2016). "Actually, about 2000 sequence variations have been documented in the CFTR gene requiring extensive and multi-step genetic testing in the diagnosis of cystic fibrosis and CFTR-related disorders." (PMID 26900683, 2016). "We thank Dr. John Riordan (University of North Carolina-Chapel Hill), and Cystic Fibrosis Foundation Therapeutics for kindly providing us with anti-CFTR antibodies." (PMID 26183966, 2015).
cystic fibrosis (continued). "Gene therapy to introduce the wild-type CFTR gene into airway epithelial cells in patients with cystic fibrosis so that they express functional CFTR has an obvious and elegant rationale." (PMID 26403534, 2015). "This clinical observation confirms the logic of targeting CFTR to treat the fundamental defect in cystic fibrosis and makes it a highly attractive strategy." (PMID 26403534, 2015). "CF is a lethal, hereditary disease caused by a mutation in the gene that codes for the cystic fibrosis transmembrane regulator (CFTR) chloride channel protein causing the misfolded CFTR protein to be degraded." (PMID 29124231, 2015). "Cystic fibrosis is a lethal disease caused by mutations in the chloride channel CFTR gene." (PMID 25626868, 2015). "In cystic fibrosis, where CFTR-dependent chloride secretion is disabled, transplanted lungs retain the ability to mount a defense against the dangers of breathing." (PMID 26059031, 2015). "An interesting initiative in this respect is the Clinical and Functional Translation of CFTR (CFTR2) project, which deals with a different ABC transporter, CFTR or ABCC7, causing cystic fibrosis (Castellani and CFTR2 team, 2013)." (PMID 26356190, 2015). "In vitro studies have shown that lumacaftor improves CFTR processing and chloride secretion in bronchial epithelial cells derived from people with cystic fibrosis homozygous for Phe508del." (PMID 26403534, 2015). "One of the therapeutic goals in cystic fibrosis has been to develop drugs which can assist the correct folding of F508del-CFTR to bypass this cellular quality control step and to restore some function." (PMID 28031875, 2015). "In 2006, Wang and colleagues observed that the down-regulation of human Hsp90 cochaperone AHA1 (AHSA1) rescues misfolding of CFTR protein in Cystic fibrosis." (PMID 26046679, 2015). "Cystic fibrosis is caused by mutations in CF transmembrane conductance regulator (CFTR)." (PMID 26701908, 2015). "Individuals with one compromised CFTR copy are carriers; individuals with both CFTR copies compromised have cystic fibrosis." (PMID 25739099, 2015). "CFTR function is normally tightly controlled as dysregulation can lead to life-threatening diseases such as secretory diarrhoea and cystic fibrosis." (PMID 25277268, 2015). "An alternative method to address the fundamental defect in cystic fibrosis is the development of genotype-specific small-molecule drugs that modulate CFTR function." (PMID 26403534, 2015). "The PAD gene list relates to a diverse set of human diseases, including cardiovascular (LMNA, MYH7), cystic fibrosis (CFTR), diabetes (HNF4A, IRS1) and migraine (ATP1A2)." (PMID 25611800, 2015). "Correction of the CFTR locus by homologous recombination in cultured intestinal stem cells from patients with cystic fibrosis." (PMID 25800748, 2015). "Our group has developed an efficient helper-dependent adenoviral (HD-Ad) vector to express the human cystic fibrosis transmembrane conductance regulator (CFTR) gene with epithelial cell specific K18 promoter for cystic fibrosis gene therapy." (PMID 26085921, 2015). "Eact, a synthetic agonist of ANO1, was synthesized for the purpose of treating cystic fibrosis in an attempt to bypass dysfunctioning CFTR channel." (PMID 25231974, 2015). "Most notably, CS induces an acquired deficiency of the cystic fibrosis transmembrane conductance regulator (CFTR), a crucial cAMP-dependent Cl- channel that is mutated in cystic fibrosis." (PMID 26066648, 2015). "CFTR has been reported to play an important role in alveolar fluid clearance in non-cystic fibrosis lungs." (PMID 25329998, 2014). "The goal of aerosolized gene therapy in treating cystic fibrosis is to restore CFTR function and normal chloride channel function in the lungs." (PMID 25505695, 2014).
cystic fibrosis (continued). "This Review outlines the roles of the cytosolic HSP70 chaperone system in the best-studied paradigms of ion-channel-misfolding disease – the CFTR chloride channel in cystic fibrosis and the hERG potassium channel in cardiac long QT syndrome type 2." (PMID 24609033, 2014). "Abnormal bioelectric properties including hyperactive ENaC activity and deficient cystic fibrosis transmembrane conductance regulator (CFTR) are well-known in cystic fibrosis lungs." (PMID 25329998, 2014). "Cystic Fibrosis is an autosomal recessive disease that arises from a defect in the Cystic Fibrosis Transmembrane Conductance Regulator (CFTR) gene." (PMID 25383714, 2014). "Ivacaftor is the first novel cystic fibrosis pharmaceutical that acts at the molecular level to potentiate cystic fibrosis transmembrane conductance regulator (CFTR) function and was first approved for clinical use in 2012." (PMID 26556432, 2014). "Cystic fibrosis is a lethal genetic disorder resulting from a mutation of the CFTR gene." (PMID 25107986, 2014). "Here we describe development and characterization of the first cystic fibrosis rat, in which the cystic fibrosis transmembrane conductance regulator gene (CFTR) was knocked out using a pair of zinc finger endonucleases (ZFN)." (PMID 24608905, 2014). "For example, Ad vectors expressing cystic fibrosis transmembrane conductance regulator CFTR have been used in phase I clinical studies to treat cystic fibrosis." (PMID 24904562, 2014). "Cystic fibrosis is an autosomal recessive disease caused by a defect in the cystic fibrosis conductance regulator (CFTR) gene located in human on chromosome 7 that mainly affects lungs, digestive and reproductive systems, but also the secretory glands, such as the endocrine and sweat glands." (PMID 25438018, 2014). "These compounds were found to overcome the processing defect of the mutant CFTR protein involved in cystic fibrosis, and to be up to 2 orders of magnitude more efficient as CFTR correctors than the clinical candidate miglustat (N-Bu-DNJ, 1)." (PMID 24991295, 2014). "The functional deficiency of the cystic fibrosis transmembrane conductance regulator (CFTR), a plasma membrane chloride channel, leads to the development of cystic fibrosis." (PMID 24970227, 2014). "Perhaps the best-studied example within this class of diseases is the channelopathy cystic fibrosis, which is caused by mutation of the cystic fibrosis transmembrane conductance regulator, CFTR (ABCC7)." (PMID 24609033, 2014). "Individuals with defective CFTR function, for example patients with Cystic Fibrosis or chronic smokers, have chronic lung infections due to a lack of clearance of respiratory pathogens." (PMID 24586903, 2014). "The CFTR gene was identified in 1989 as the gene mutated in cystic fibrosis." (PMID 24714160, 2014). "This suggests that inflammation might be the earliest event in the CF lung causing damage and thus predisposing to infection, and that the basic defect in cystic fibrosis transmembrane regulator (CFTR) itself may initiate or amplify inflammation." (PMID 24885444, 2014). "One example of this is in cystic fibrosis, where the degradation of certain mutant, but functional, versions of the chloride channel, CFTR, leads to a lowered amount of channel protein and manifestation of the disease." (PMID 24497846, 2014). "We thank Alyssa Fournett for her critical reading of the manuscript and acknowledge the Cystic Fibrosis Foundation reagent distribution program and Dr. John Riordan for the CFTR antibody used in this research." (PMID 25184794, 2014). "However, epidemiological investigations and animal models also support a direct causal link between inactivation of skeletal cystic fibrosis transmembrane regulator (CFTR), the gene that when mutated causes CF, and CFBD." (PMID 24236172, 2013). "In cystic fibrosis a defect in the cystic fibrosis transmembrane conductance regulator (CFTR) gene produces a chloride-ion channel defect in epithelial cells." (PMID 23383288, 2013).